KRAS (KRas proto-oncogene, GTPase)
Diseases named in the same sentence as KRAS in open-access papers (continued):
Sharing a sentence is not in itself a finding about the gene and the disease.
cancer (continued). "Neoantigens derived from somatic mutations in Kirsten Rat Sarcoma Viral Oncogene Homolog (KRAS), the most frequently mutated oncogene, represent promising targets for cancer immunotherapy." (PMID 38684865, 2024). "In a mutant Kirsten rat sarcoma viral oncogene homolog (KRAS)‐like‐dependent human cancer cell line such as in Mia PaCa‐2 cells, the inactivation of GSK3‐β induces apoptosis via the accumulation of β‐catenin." (PMID 39632551, 2024). "Burst keywords show that previous studies have concentrated on assessing the effectiveness of EGFR inhibitors and investigating combination therapies among patients with KRAS-mutant cancers." (PMID 38706597, 2024). "Hippo signaling components at the heart of oncogenic adaptations fuel the development of drug resistance in many cancers for targeted therapies including KRAS and EGFR mutants." (PMID 38607003, 2024). "These investigations have also identified four potential EGCG target proteins linked to cancer development: IKBKB, KRAS, WEE1, and NTRK1." (PMID 38978121, 2024). "A potential treatment for suppressing KRAS-mutant cancer progression is blocking the small ubiquitin-like modifier (SUMO) pathway." (PMID 38992694, 2024). "The most common putatively actionable alterations across all of the 35 cancer types were mutations in PIK3CA, KRAS and PTEN." (PMID 38890488, 2024). "Co‐targeting of CDK9 and KRAS/MAPK signaling pathways eliminates ERK‐MYC activation and prevents feedback activation mediated by receptor tyrosine kinases, leading to more effective control of KRAS‐mutant cancers and overcoming KRASi resistance." (PMID 39254172, 2024). "For these reasons, combination therapies investigating the ability to target downstream metabolic pathways and restore metabolic homeostasis in cancer cells are becoming increasingly important for KRAS p.G12C inhibitors." (PMID 39001451, 2024). "Clinical trials reveal the effectiveness of ICBs and the promising potential of T-cell receptor T-cell therapy and vaccines in treating KRAS-mutant cancers." (PMID 39252322, 2024). "Being a key signaling protein in cancer, we investigated how the many existing experimental KRAS structures compared to AI predictions, and how conformational heterogeneity within an individual fold type can drive biological phenomena." (PMID 39591473, 2024). "For the past ten years, the publication volume in KRAS-related cancer has generally increased steadily, with the growth rate peaking in 2014 and the highest number of publications occurring in 2021." (PMID 38706597, 2024). "DNA of exosomal mutant KRAS causes this transformation, as evidenced by the increased presence of FoxP3 + Tregs in cancer tissues of mutant KRAS patients compared to those with wild type (WT) KRAS." (PMID 38553754, 2024). "Using genomic DNA from human cancer cells with mutant and wild-type KRAS, we confirmed that PROMER PCR can detect mutant DNA." (PMID 38938409, 2024). "HSF1 is a downstream effector of the RAS-MEK pathway and KRAS-mutant cancers, due to their elevated levels of cellular stress resulting from rapid proliferation and metabolic demands, have a higher dependence on HSF1." (PMID 39850800, 2024). "From a vertical signaling cascade standpoint, the three commonly mutated effectors of the ERKp in human cancer are arranged as EGFR, KRAS, and BRAF." (PMID 38485987, 2024). "Relevant aspects range from KRAS-dependent oncogenesis to mechanisms of resistance to KRAS inhibitors, epigenetics in KRAS mutant tumors, KRAS signaling in cancer immunity, and KRAS synthetic lethality." (PMID 38275900, 2024).
cancer (continued). "We subsequently evaluated BAY 11-7082’s efficacy in inhibiting the tumorigenic potential of cancer cells expressing oncogenic NRAS, KRAS, and HRAS mutations." (PMID 38982514, 2024). "The altered cancer metabolism results in an active glucose absorption necessary for accelerated cell growth, which is especially relevant for KRAS mutant cancer cells." (PMID 38473779, 2024). "Kirsten rat sarcoma viral oncogene homolog (KRAS) is the most well-known oncogene and has the highest mutation rate across all cancers." (PMID 39575418, 2024). "We next focused on the adenocarcinomas and looked into the common cancer gene mutations in EGFR and KRAS." (PMID 38473297, 2024). "Targeting the Hippo signaling pathway to overcome intrinsic and acquired resistance to KRAS-targeted therapy in cancer." (PMID 39704172, 2024). "This comprehensive review and bibliometric analysis have illuminated the rapidly evolving landscape of immunotherapy in the context of KRAS-mutant cancers." (PMID 39252322, 2024). "This study reveals the CDK9/PP2A/ERK network involved in transcriptional pause release and complement activation in KRAS‐mutant cancers, which limits the efficacy of CDK9i in vivo." (PMID 39254172, 2024). "In the Cancer Cell Line Encyclopedia, BRAF class 3–mutated NSCLC cell lines showed greater sensitivity to EGFR-TKIs compared with BRAF class 2–mutated and KRAS-mutated lines." (PMID 39637338, 2024). "The siREN study, investigating Ras-effector interactions in KRAS-mutant cancer, used single cell analysis to interrogate cell viability, reactive oxygen species generation, growth, proliferation and cell death associated with effector knockdown." (PMID 39372214, 2024). "We discovered that TAK-981 downregulated the expression of the currently undruggable MYC and effectively suppressed the growth of MYC-expressing KRAS-mutant cancers across different tissue types." (PMID 38992694, 2024). "Previous studies have shown that KRAS-driven cancers rely less on fatty acid oxidation for steady-state proliferation, shifting toward lipolysis and the oxidation of stored lipids during invasion and metastasis." (PMID 39195509, 2024). "To explore the role of mutant KRAS in modulating the cancer stem cell landscape in CRC, we selected three CRC cell lines (HCT116, HCT15, and SW480), all harboring a KRAS mutation, though with different origins and genetic profiles." (PMID 39061234, 2024). "Collectively, the results herein provide a mechanism-based preclinical and translational rationale, and support a distinct therapeutic opportunity in targeting BAD-mediated survival; and concurrently inhibiting pBADS99 and MEK in KRAS-mutant cancers." (PMID 38409090, 2024). "These vaccines are designed to induce antigen-presenting cells to display mutant KRAS, stimulating attacks by cytotoxic T-cells against cancer cells expressing mutant KRAS neoantigen." (PMID 38668053, 2024). "In patients with cancer types seldom presenting the G12C mutation, like PDAC and CRC, where these mutations represent less than 1.5% and 7% of all KRAS mutations, respectively, sotorasib has also shown some promising clinical activity." (PMID 39164274, 2024). "In the past few years, intensive work by the research community has led to breakthroughs in the treatment of KRAS-mutant cancers, especially in the G12C mutant form." (PMID 39687047, 2024). "Recently, high-dose VC applications became an attractive approach in cancer therapy, especially for KRAS mutant cancers, and it is a topic of ongoing research." (PMID 38473779, 2024).
cancer (continued). "The etiology of the predominance of specific base changes resulting in amino acid alterations in KRAS for different cancers is not fully understood." (PMID 39001385, 2024). "By further examining cancer stage, we have identified a prognostic value of pCASTOR1 level in early-stage LUAD male patients with KRAS mutations." (PMID 39385301, 2024). "For a long time, KRAS was considered “undruggable,” but recent studies have identified therapies targeting specific KRAS mutations, especially in treating predominantly RAS-driven cancers." (PMID 38982514, 2024). "Upon Gln deprivation, KRAS-driven cancer cells enter the S phase and arrest due to insufficient nucleotide biosynthesis." (PMID 39272883, 2024). "In summary, our data demonstrate that simultaneous inhibition of CDK9 and the KRAS/MAPK pathway reciprocally strengthen the anticancer effect of each monotherapy in preclinical models of KRAS‐mutant cancers, including those with KRASi resistance." (PMID 39254172, 2024). "Gene mutations in KRAS cause constitutive activation of the KRAS protein and MAPK/AKT signaling, resulting in unregulated proliferation and survival of cancer cells and other aspects of malignant transformation, progression, and metastasis." (PMID 38978742, 2024). "Next, we explored the potential contribution of Id1 to the acquired resistance to trametinib-mediated apoptosis, a core mechanism of trametinib-mediated cancer cell death, in TR KRAS-mutant mouse and human LUAD cells." (PMID 38643157, 2024). "Here, we present the direct characterization of the secreted protein profiles between CAFs and KRAS mutant-cancer cell lines from colorectal, lung, and pancreatic tissues using multiplexed mass spectrometry." (PMID 38767394, 2024). "The prognostic role of STK11 mutations in combination with co-occurring alterations in other cancer genes is being evaluated in various studies, with poor ICI outcomes observed in patients with low TMB or KRAS co-mutation." (PMID 39045411, 2024). "Given the formidable challenge posed by KRAS-mutant cancers, it is imperative to provide a concise overview of drug classifications, resistance mechanisms, and potential strategies to overcome them." (PMID 38706597, 2024). "Mutation and activation of the three RAS genes (KRAS, HRAS, and NRAS) are recognized in about 25% of human cancers, with Kirsten Rat Sarcoma viral oncogene homolog (KRAS) playing a significant role in the development of tumors." (PMID 38309290, 2024). "The KRAS gene belongs to the RAS family, which is one of the common oncogenes in cancer, with a variety of mutation sites, the most common of which include G12C, G12D, and G12V." (PMID 40231011, 2024). "A variety of cancer-specific targets have been leveraged for CRISPR-based anti-cancer therapy, including gene fusions, mutant KRAS, and indel mutations." (PMID 38915758, 2024). "We also demonstrated that an irreversible covalent inhibitor of SRC, DGY-06-116, which targets cysteine-277 in the P-loop, enhances the antitumor activity of MRTX849 in multiple KRAS-G12C cancers." (PMID 39661665, 2024). "In KRAS-driven cancers like PDAC, calmodulin plays a dual role in regulating the activation of the MEK/ERK and PI3K/AKT pathways." (PMID 39682132, 2024). "Inhibition of YAP/TAZ strikingly enhances the sensitivity of KRAS G12D–mutant cancer cell lines to KRAS G12D inhibitor." (PMID 39704172, 2024).
cancer (continued). "The activity of the Hippo pathway transcription factors substitutes for the activity of oncogenic KRAS G12C in cancer cells treated with inhibitors of KRAS, leading to treatment resistance through activation of the PI3K/AKT cascade and MYC activation." (PMID 39768557, 2024). "KRAS is the most common subtype among RAS mutations and is correlated with poor prognosis in cancer patients." (PMID 39926600, 2024). "In this study, we demonstrated the immune-independent effects of TAK-981 and its combination with the MEK inhibitor trametinib in MYC-expressing KRAS-mutant cancers." (PMID 38992694, 2024). "KRAS G12C–mutant cancer cell lines with either intrinsic or acquired resistance to KRAS G12C inhibitors display cross-resistance to other inhibitors targeting upstream or downstream components of the RAS signaling pathway." (PMID 39704172, 2024). "Activation of YAP/TAZ drives KRAS G12C–mutant cancer cells to acquire resistance to KRAS G12C inhibitors." (PMID 39704172, 2024). "KRAS-4B has been shown to be most expressed across a range of cancer cell lines and healthy mouse tissue, followed by KRAS-4A, NRAS and lastly HRAS." (PMID 39372214, 2024). "By adopting a more comprehensive approach that addresses both cancer cells and their supportive environment, we can pave the way for more successful treatments for KRAS-mutant CRC." (PMID 39061234, 2024). "Given these obstacles, the majority of KRAS-mutant cancers continue to be treated with conventional cytotoxic chemotherapies." (PMID 38822082, 2024). "Many treatments for KRAS-mutant cancers, including epigenome-targeted drugs, are currently under investigation." (PMID 38992694, 2024). "We recently discovered the effectiveness of blocking small ubiquitin-like modifier (SUMO) signaling cascade (SUMOylation) in MYC-expressing KRAS-mutant cancer cells using a SUMO-activating enzyme E inhibitor TAK-981 that results in SUMOylation inhibition." (PMID 39334463, 2024). "PCAIs are a novel class of agents designed to target and disrupt the activities of KRAS and other G-proteins that are hyperactive in various cancers." (PMID 38540084, 2024). "There was a significant enrichment of YAP-associated transcripts in DTPs across EGFR-mutant, ALK fusion-positive, and KRAS-mutant cancer cell." (PMID 38702301, 2024). "Research focused on NSCLC with KRAS driver mutations, in particular, the KRAS p.G12C mutation, shows that co-mutations in STK11 and/or KEAP1 make these cancers notably resistant to standard therapies, including targeted and immune-based treatments." (PMID 39001451, 2024). "We found that TAK-981-induced MYC downregulation promoted the activation of STING followed by Stat1 and MHC class I in KRAS-mutant cancer cells." (PMID 39334463, 2024). "It was found that YAP1 substitutes for the loss of oncogenic KRAS in human cancers and that YAP1 expression is required for KRAS-induced cell transformation." (PMID 39456549, 2024). "The combinatorial potential of such an agent for the treatment of KRAS-mutant cancers is noteworthy." (PMID 38992135, 2024). "Here, we developed multiple models of acquired resistance to second generation, dual-mechanism ERK/MAPK inhibitors to characterize transcriptionally-mediated resistance in KRAS-mutant cancers." (PMID 38822082, 2024). "It is noted that FSP1 is also upregulated in KRAS-mutant cells and is responsible for ferroptosis resistance and thus, combining FSP1 inhibitors with ferroptosis induction is proposed to be an efficient therapy of KRAS-mutant cancers." (PMID 38908072, 2024).
cancer (continued). "In fact, in the Catalogue of Somatic Mutations in Cancer (COSMIC v.98), 6 cases of the c.30_35dup mutation are reported out of 49,887 cases of KRAS mutation." (PMID 38796063, 2024). "Low expression of let-7 in human cancer correlates with high KRAS expression (at least in lung, breast and colorectal)." (PMID 38637419, 2024). "Small molecule inhibitors of the KRAS(G12C) oncoprotein have demonstrated clinical efficacy in patients with multiple cancer types and have led to regulatory approvals for the treatment of non-small cell lung cancer." (PMID 38589574, 2024). "The bibliometric analysis revealed a marked increase in research activity, particularly from the United States and China, emphasizing the global commitment to tackling KRAS-mutant cancers." (PMID 39252322, 2024). "Decades of research on targeting KRAS in cancer has finally removed the “undruggable” tag from mutant KRAS." (PMID 38464238, 2024). "KRAS mutant cancer cells showed distinct transcriptional features, reduced differentiation and low levels of aneuploidy." (PMID 38418883, 2024). "In cancer, upregulated oncoproteins KRAS, MYC, CCNE1, etc. act as primary sources of replicative stress, while also impairing the cell’s ability to adequately respond to such stress." (PMID 38669256, 2024). "WT RAS isozymes, NRAS and HRAS, are co-expressed in KRAS mutant cancer cells whereby their proliferation can be driven not only by mutant KRAS, but also by extracellular mitogens that activate WT RAS isozymes." (PMID 38978742, 2024). "We provide evidence that sonidegib suppresses re-expression of KRAS in cancer cells treated with a KRAS inhibitor." (PMID 38225225, 2024). "The combination therapy of dasatinib or bosutinib with MRTX849 effectively eliminated MRTX849-resistant KRAS-G12C–mutant cancer cells in mouse models or organoid models, with minimal observed side effects." (PMID 39661665, 2024). "Because of the high prevalence of the alteration, KRAS has been an attractive treatment target for cancer." (PMID 38756650, 2024). "This study reveals the intricate relationship between KRAS mutation and signaling markers (ERK, AKT, P65) in cancer." (PMID 38465160, 2024). "Here, it is important to note that KRAS, together with HRAS and NRAS expressed genes belong to the RAS family of proteins that are proto-oncogenes and are frequently mutated in human cancers." (PMID 39493299, 2024). "This article offers a review of both fundamental and translational research leveraging the CRISPR system in the context of KRAS-mutant cancer." (PMID 38275900, 2024). "Approximately ninety percent of PDACs are associated with mutations in Kirsten rat sarcoma (KRAS) and as a result are considered to be the most “RAS addicted” of all human cancers." (PMID 38802657, 2024). "Although KRAS mutants display different features in terms of frequency among cancers, impact on KRAS biochemical activity and oncogenic potential, they have been usually classified as a homogenous group." (PMID 38261067, 2024). "Preclinical evidence suggests that the inhibition of SOS1 attenuates feedback reactivation induced by MEK inhibitors in KRAS-dependent cancers improving sensitivity to MEK inhibitors." (PMID 38756650, 2024). "Our findings provide strong rationale that the state of myeloid cells significantly influences I/O responses and highlights the need for combining KRAS cancer-targeted therapy with myeloid activating I/O to enhance and prolong antitumor effects." (PMID 38727236, 2024). "We then turn to the covalent inhibition of KRAS (Kirsten rat sarcoma viral oncogene), a protein target prevalent in numerous types of cancers." (PMID 39043787, 2024). "The RAS family oncogenes, namely, KRAS, NRAS and HRAS, represent the most prevalently mutated genes across human cancers." (PMID 39877159, 2024). "Despite the promising advancements, our review also identifies significant gaps in the current understanding and application of immunotherapy in KRAS-mutant cancers." (PMID 39252322, 2024).